RN7SL788P (RNA, 7SL, cytoplasmic 788, pseudogene)
Gene: Miscellaneous RNA gene on chromosome 1 (52,150,104 to 52,150,419, forward strand). Ensembl gene ENSG00000241745.
Homologues: Orthologues: chimpanzee Metazoa_SRP (99% identical), macaque Metazoa_SRP (82% identical). Paralogues in human: RN7SL1 (80% identical), RN7SL2 (80% identical), RN7SL566P (80% identical), RN7SL3 (79% identical), RN7SL126P (78% identical), RN7SL220P (78% identical), RN7SL127P (78% identical), RN7SL714P (78% identical), RN7SL45P (77% identical), RN7SL672P (77% identical), Metazoa_SRP (77% identical), RN7SL478P (77% identical), and 701 more.